DCN (decorin)
Diseases named in the same sentence as DCN in open-access papers (continued):
Sharing a sentence is not in itself a finding about the gene and the disease.
breast carcinoma (continued). "Global expression profiles comparing human breast carcinoma in decorin treated when compared to vehicle control showed that most of the genes in two independent experiments (n = 6 each) showed close grouping with only minor changes." (PMID 23029096, 2012). "We thus sought to evaluate the tumoricidal benefits of systemic decorin on a triple-negative orthotopic breast carcinoma xenograft model." (PMID 23029096, 2012). "Thus, the expression and/or activity of decorin could affect breast cancer risk." (PMID 23029096, 2012). "The results show that decorin protein core (henceforth designated decorin) was capable of retarding the growth of the breast carcinoma xenografts, which was highly significant at day 23 (P<0.001)." (PMID 23029096, 2012). "In the majority of patients with breast cancer, increased staining for versican and decorin was found, in the peritumoral and intratumoral stroma." (PMID 21791066, 2011). "The expression of decorin was markedly elevated in breast carcinomas and normal tissues that are characterized by increased MD and MAMCs." (PMID 21791066, 2011). "In human breast cancer tissues, decorin levels were decreased 2-5-fold when compared to normal breast tissue." (PMID 20092659, 2010). "Abnormal expression of decorin has been found in many tumors, including lymphoma and human breast carcinoma." (PMID 20092659, 2010). "It has been shown that decorin functionally inactivates the ErbB2 protein in breast carcinoma cells, leading to growth suppression and cytodifferentiation of mammary carcinoma cells." (PMID 20092659, 2010). "Injection of decorin protein into mammary carcinoma rodent models resulted in a marked reduction in both primary tumor growth and metastatic spread compared with animals injected with vehicle alone." (PMID 19036156, 2008). "Decorin could provide a mechanical strengthening of the fibrils inside each fiber of the concentric collagen lamellae surrounding breast cancer ducts." (PMID 40643556, 2025). "This indicates that breast cancer cells and rIL-6 downregulated DCN and activated NBFs." (PMID 38667295, 2024). "In vitro studies have demonstrated its anti-tumorigenic effects through transforming growth factor-β signaling and decreased cell adhesion with recombinant decorin supplementation in specific breast cancer cell lines (BT474, T47D, SKBR3, HCT8/E11, SW480, and CaCo-2)." (PMID 39716322, 2024). "An oncolytic adenovirus carrying DCN (rAd.DCN) has previously been developed, demonstrating inhibitory effects on breast cancer, as well as inhibiting tumor growth and lung metastasis of breast cancer and bone metastasis of prostate cancer in mouse models." (PMID 39482550, 2024). "Interestingly, breast cancer cells and the recombinant IL-6 protein, both known to activate fibroblasts in vitro, downregulated DCN in BSFs." (PMID 38667295, 2024). "Notably, decorin expression decreases progressively across the breast cancer stages with DCIS (n = 89) having increased decorin expression compared to IBC (n = 98)." (PMID 39716322, 2024). "In addition to syndecan‐1, elevated circulating levels of decorin and glypican‐4 were found in breast cancer patients." (PMID 39600538, 2024). "Notably, PGC1-α activates FNDC5 to increase the secretion of Irisin and decorin evokes mitophagy in breast carcinoma cells via PGC-1α and mitostatin." (PMID 35159071, 2022). "DCN upregulation can predict a good prognosis in breast cancer patients." (PMID 35615145, 2022). "Therefore, in this Review, we examine the role of decorin in orchestrating and evoking mitochondrial autophagy within breast cancer." (PMID 35159071, 2022). "The role of fibromodulin and decorin for radiotherapy response in HNSCC is still unknown, but in a breast cancer cell line, 4T1, overexpression of FMOD and DCN was associated with downregulation of NF-κB and TGF-β1." (PMID 34283070, 2021).
breast carcinoma (continued). "DCN expression was also significantly lower in breast tumors than in normal breast tissues, and in the more aggressive basal-like breast cancer subtype compared with the luminal subtype." (PMID 33452400, 2021). "In line with this, decorin directly activated mitophagy in breast carcinoma cells trough Met receptor activation and subsequent mobilization of PGC-1α (Peroxisome proliferator-activated receptor-γ co-activator 1-α), accompanied by a decorin-mediated mRNA stabilization accumulation of Mitostatin." (PMID 34917515, 2021). "Moreover, high DCN expression in patients with breast cancer correlated with better survival outcomes." (PMID 33452400, 2021). "Decorin down-regulation is mediated by secreted growth factors in an autocrine and paracrine (due to the interaction with breast cancer cells) manner, with bFGF and VEGF being the key players of this regulation in young and senescent breast stromal fibroblasts." (PMID 33924197, 2021). "Since we identified that stromal DCN was attenuated in the surrounding tissue of tumors with invasive components, we analyzed the correlation between the stromal expression and plasma concentration of DCN to the different stages of breast cancer." (PMID 34884232, 2021). "Decorin has been reported to be significantly expressed in both healthy and various malignant conditions of human breast tissue but presents a stroma-exclusive distribution even in breast cancers, as human breast malignant cells have been shown to hardly express and synthesize decorin." (PMID 33924197, 2021). "It has been widely described the anti-metastatic role of decorin (DCN1) in breast cancer." (PMID 32525929, 2020). "Finally, we assessed if the rescue of decorin or NOV expression in the presence of EO CM would return breast cancer proliferation to that seen upon exposure to EO CM alone." (PMID 30813947, 2019). "Indeed, in vivo and in vitro studies have strongly suggested that DCN blocks the growth and distant metastasis of breast cancer cells by down-regulating EGFR expression and interfering with the formation of EGFR/ErbB2 dimers." (PMID 29435195, 2018). "Interestingly, studies in a triple-negative orthotopic breast carcinoma xenograft models, showed an unexpected and paradoxical role for the DCN protein core in inhibiting genes that were necessary for immunomodulatory responses." (PMID 29435195, 2018). "Furthermore, decorin adenoviral transduction has been demonstrated to decrease the malignant behaviour of breast cancer cells and even to suppress their capability to form bone metastasis." (PMID 28653173, 2017). "Additionally, by immunoprecipitation and mass spectrometry, we confirmed that decorin forms a complex with periostin in both phyllodes tumors and BT-20 breast cancer cells." (PMID 25400079, 2014). "There have been recent reports of the anti-tumor effects of decorin on various malignant tumors, including uterine cervical carcinoma cells, ovarian cancer cells, colon carcinoma cells, breast cancer cells, and pancreatic cancer cells." (PMID 25244916, 2014). "Our results reveal the molecular details of the periostin–decorin complex in both phyllodes tumor tissues and breast cancer cells; this interaction may represent a novel target for anti-cancer therapy." (PMID 25400079, 2014). "SKBR3 was the only other breast cancer cell line of which CM downregulated decorin." (PMID 25593993, 2014). "Expression of the proteoglycans lumican and decorin has been found to be increased in stromal tissue associated with breast cancer and, in the absence of cancer, in women with extensive mammographic density." (PMID 25010427, 2014). "Moreover, reduced decorin within tumor stromal cells has been established as a poor prognostic factor for invasive breast cancer and in murine models of spontaneous breast cancer with mammary gland carcinogenesis." (PMID 25244916, 2014).
breast carcinoma (continued). "As we have shown in human breast cancer, these analyses clearly demonstrated that also in human bladder cancer all areas and islets populated by malignant cells were completely devoid of decorin mRNA and immunoreactivity." (PMID 24146840, 2013). "Previously, decreased level of decorin expression has been reported in breast cancer." (PMID 23007289, 2013). "However, in a recent study, even increased amounts of decorin in breast carcinoma has been observed." (PMID 23007289, 2013). "Furthermore, systemic delivery of decorin protein core to breast carcinoma xenografts has been reported to modulate the expression of several hundred stromal genes creating an unfavourable tumour microenvironment for tumour progression and metastasis." (PMID 24146840, 2013). "Moreover, recombinant decorin proteoglycan or decorin protein core inhibits metastatic spreading of breast carcinoma xenografts." (PMID 23029096, 2012). "A possible scenario for the involvement of both proteoglycans in breast cancer progression may involve the accumulation of both versican and decorin by stromal fibroblasts in response to estrogens, growth factors and cytokines." (PMID 21791066, 2011). "In the present study, we have evaluated the expression of versican and decorin in non-palpable breast carcinomas and their association with high risk mammographic findings and tumor characteristics." (PMID 21791066, 2011). "Decorin has been shown to inhibit the growth of both primary breast cancer xenografts and metastatic spread by inactivating the oncogenic ErbB2 protein in breast carcinoma cells and downregulating members of the ERb tyrosine kinase family, leading to growth inhibition." (PMID 20398359, 2010). "Treatment with decorin protein reduced primary tumor growth by 70% and eliminated observable metastasis in an orthotopic mammary carcinoma animal model injected with a metastatic breast cancer cell line." (PMID 20092659, 2010). "We investigated associations of 14 common polymorphisms in the DCN and LUM genes with 798 breast cancer cases and 843 controls from Mayo Clinic, MN, USA." (PMID 19036156, 2008). "Interestingly, the secretome from a series of both untreated and irradiated human breast cancer cell lines with different molecular profiles inhibited decorin expression in young and senescent stromal fibroblasts, which was annulled by SU5402, a bFGF and VEGF inhibitor." (PMID 33924197, 2021). "Indeed, the importance of decorin as a modifier of the TME in breast cancer has to be recognized." (PMID 28653173, 2017). "Thus, our study provides evidence that targeted decorin transduction to breast cancer cells could be used as a novel adjuvant therapy in the treatment of human breast cancer in the future." (PMID 23007289, 2013). "In addition, induction of apoptotic features of MCF7 cells due to decorin transduction may also have a role in the finding of this study that decorin-transduced MCF7 human breast cancer cells exhibit decreased proliferation." (PMID 23007289, 2013). "DCN rs3138165 was positively associated with breast cancer risk in the Mayo Clinic sample but the finding was not confirmed in the SEARCH sample." (PMID 19036156, 2008). "The content of decorin, small leucine-rich proteoglycans (SLRPs) that specifically bind to collagen fibrils, changes from the TACS-II to the TACS-III stage in breast cancer." (PMID 40643556, 2025). "Decorin has previously been shown to activate autophagy in endothelial cells, through VEGFR2/AMPKα activation and mTOR inhibition, and in breast carcinoma cells and activates autophagy flux in glioma cells and intestinal cells." (PMID 35787306, 2022). "DCN signaling is mediated through the ERK and AKT pathways in breast cancer cells, endothelial cells, and myoblasts." (PMID 36500314, 2022). "Systemic delivery of an oncolytic adenovirus expressing decorin induced, among other effects, mitochondrial autophagy in MDA-MB-231 breast cancer cells." (PMID 32847060, 2020).
breast carcinoma (continued). "Decorin also activates ERBB4, which blocks the phosphorylation of heterodimers containing either ERBB2 or ERBB3, thereby suppressing cell growth in mammary carcinoma cells." (PMID 31157165, 2019). "It is suggested that lower expression of decorin weakens the ECM and is correlated with rapid progression, higher recurrence, and poor survival rate in breast cancer patients." (PMID 28083513, 2016). "Three colorectal cancer cell lines (CaCo-2, HCT8/ E11 and SW480) and three breast cancer cell lines (BT474, SKBR3 and T47D) were seeded onto coatings of purified decorin in different concentrations, or type I collagen (10 μg/ml in PBS)." (PMID 25593993, 2014). "As can be expected, several other studies supporting the antitumor and antimetastatic activity for decorin have been published, and low levels of decorin have been found to be associated with a shorter progression time and poorer survival in lymph node-negative invasive human breast carcinomas." (PMID 23007289, 2013). "Decorin was expressed in normal mammary gland tissues of five month-old TA2 mice (Group A) and breast cancer-bearing TA2 mice (Group B), as well as in breast cancer tissues from TA2 mice (Group C)." (PMID 20092659, 2010). "This is the first study to investigate not only the distinct and independent effects of different exercise modes on anti-cancer myokines such as decorin, IL-6, OSM, and SPARC in survivors of breast cancer, but also in exploring the effects of such exercise modes on MDA-MB-231 cell growth in vitro." (PMID 40608178, 2025). "Therefore, it is critical to investigate the acute effects of different exercise modes on the expression of anti-cancer myokines, such as IL-6, OSM, decorin, and SPARC, and their effects on breast cancer cell growth (i.e., MDA-MB-231)." (PMID 40608178, 2025). "Similarly, it has been previously shown that decorin negatively regulates the expression of VEGF-A and HIF-1α in breast cancer cells." (PMID 38667295, 2024). "Decorin (DCN), a member of the small leucine-rich proteoglycan gene family, is secreted from stromal fibroblasts with non-cell-autonomous anti-breast-cancer effects." (PMID 38667295, 2024). "Indeed, decorin binds VEGFR2 expressed by the endothelial cells and MET that abundantly (that is, target-rich) adorns breast cancer cells." (PMID 35159071, 2022). "Although the antitumor functions of DCN in lung adenocarcinoma and breast cancer have been identified, the DCN action mechanism in CC has not yet been explored." (PMID 35420507, 2022). "We discovered that nanomolar amounts of soluble, monomeric decorin evokes protracted and non-canonical endothelial cell autophagy and breast cancer cell mitochondrial autophagy (mitophagy), directly within the tumor parenchyma." (PMID 35159071, 2022). "Despite provoking their cell cycle arrest, ionizing radiation did not seem to alter the secretome of breast cancer cells, at least regarding its ability to restrain decorin expression in human breast stromal fibroblasts." (PMID 33924197, 2021). "Although, no studies to date have demonstrated their roles in breast cancer, BGN and DCN have been implicated in the development and progression of endometrial, bladder, colon, blood or lung cancers." (PMID 34162438, 2021). "They demonstrate that decorin acts as a tumor suppressor in cancer cells and human xenograft mouse models by destabilizing the E-cadherin-EGFR signaling axis, and their findings suggest potential therapeutic strategies for this aggressive breast cancer." (PMID 33452400, 2021). "EO effects on breast cancer proliferation were mediated by NOV and decorin." (PMID 30813947, 2019). "Moreover, when an antibody to decorin was added to EO CM plus recombinant decorin protein, both MDA-MB-231 and MCF-7 (green line) breast cancer cell proliferation were restored to levels at or below that of the addition of EO CM alone (blue line)." (PMID 30813947, 2019).
breast carcinoma (continued). "We also found that the CM from EOs reduced the proliferation of both triple-negative and ER+ breast cancer cells and that this effect could be mediated by either NOV or decorin." (PMID 30813947, 2019). "In all, our previous results together with the present study support the proposal that, mesenchymal and epithelial breast cancer cells are not able to synthesize decorin." (PMID 28653173, 2017). "Recently, we have shown that adenovirus mediated transduction of decorin to decorin negative breast cancer cells (MCF-7) decreased proliferation and increased apoptosis of the cells." (PMID 24146840, 2013). "Our study also shows that transduction of decorin in decorin-negative human breast cancer cells markedly modulates the growth pattern of these cells." (PMID 23007289, 2013). "Recently, we have shown that in various forms of human breast cancer, decorin is not expressed by cancer cells." (PMID 24146840, 2013). "The mechanism(s) of action of decorin transduction on the behavior of MCF7 human breast cancer cells was not in our focus in this study and therefore remains to be explored." (PMID 23007289, 2013). "We found that the elevated expression of decorin and versican by stromal fibroblasts in non-palpable breast carcinomas with MAMCs is positively correlated with the higher expression of ERα and PR by tumor cells." (PMID 21791066, 2011). "A similar increase in decorin expression was noticed to the tumor stroma in non-palpable breast carcinomas with high MD and MAMCs." (PMID 21791066, 2011). "We hypothesized that genetic variation in the decorin (DCN) and lumican (LUM) genes may contribute to breast cancer." (PMID 19036156, 2008). "Furthermore, the proteoglycan decorin (DCN), which is known to be downregulated in breast cancer and has demonstrated both anti-proliferative and anti-metastatic properties, was significantly reduced in late-stage tumours compared to healthy fatpad in our data (C3)." (PMID 35933466, 2022). "Decorin down-regulation is mediated by PDGF, EGF, IGF-I, TGF-β and principally by bFGF secreted by the stromal cells themselves acting in an autocrine manner, as well as that released by the neighboring aggressive breast cancer cells establishing a paracrine effect." (PMID 33924197, 2021). "Given the reported paracrine effect of soluble factors secreted by breast cancer cells on breast stromal fibroblasts —we assessed the effect of selected exogenous and paracrine growth factors (i.e., PDGF, bFGF, EGF, IGF-I and TGF-β) on the transcriptional regulation of decorin." (PMID 33924197, 2021). "Breast cancer cells, in turn, secrete periostin that sequesters DCN and by doing so the cancer cells provide themselves an opportunity to grow invasively and migrate without inhibitory activity from DCN." (PMID 26697491, 2015). "Regarding decorin in breast malignancies the published data are conflicting, i.e., whether breast cancer cells express it or not." (PMID 23007289, 2013). "However, ISH results clearly demonstrated that human breast cancer cells independently of the type of the cancer do not express decorin mRNA." (PMID 23007289, 2013). "Our results using ISH with DIG-labeled decorin probe have clearly shown that human breast cancer cells do not express decorin at all and that in human breast tissue specimen decorin is derived from original stromal cells, not from benign or malignant tumor-forming epithelial cells." (PMID 23007289, 2013). "Exercise has been shown to lead to upregulated systemic DCN in breast cancer patients, but without demonstrating a direct relationship between systemic DCN levels and clinical outcome, and in prostate cancer patients, exercise had no direct effect on systemic DCN levels." (PMID 41392017, 2026). "However, results on decorin expression in human breast cancer have been somewhat conflicting, i.e., whether breast cancer cells express this small proteoglycan or not." (PMID 23007289, 2013).